MAFF (MAF bZIP transcription factor F)
Diseases named in the same sentence as MAFF in open-access papers (continued):
Sharing a sentence is not in itself a finding about the gene and the disease.
tumor (20 papers, 2020 to 2026). "When MAFF was re-expressed with wobble mutations in these knockdown cells, inhibition of tumor cell invasion was rescued." (PMID 34262028, 2021). "Driving lipid metabolic reprogramming and immunosuppression through MIF-(CD74+CD44)-mediated macrophage polarization, our work finds FOS as a master regulator of the malignant C0 MAFF+ tumor cell subtype in LUAD." (PMID 40936936, 2025). "In HCC, all-trans retinoic acid (ATRA) enhances TFPI2 via retinoic acid receptor alpha (RARα), modulated by MAF bZIP transcription factor B (MAFB, activator) and MAFF (repressor), influencing tumor invasion." (PMID 40361374, 2025). "We discovered that invasive LUAD was dominated by a highly stem-like C0 MAFF+ tumor cell subtype that produced chemokines and activated lipid metabolism." (PMID 40936936, 2025). "The findings revealed that C0 MAFF+ TCs acted as senders, mediators and influencers, whereas macrophages primarily functioned as influencers, senders and mediators, which could have been linked to the conversion of regular macrophages into tumor-associated macrophages (TAMs)." (PMID 40936936, 2025). "For a deeper understanding of the oncogenic mechanisms of the C0 MAFF+ tumor cell subtype, we analyzed the TFs within this subtype and identified the top five active TFs: KLF6, ATF3, JUN, FOS, and FOSB." (PMID 40936936, 2025). "The synergy among these genes effectively demonstrated the C0 MAFF+ tumor cell subtype’s role in promoting tumorigenesis." (PMID 40936936, 2025). "To identify binding partners of MAFF involved in tumor cell invasion and metastasis, we first performed affinity purification and mass spectrometry (AP-MS)." (PMID 34262028, 2021). "Consistent with the effects on MDA-MB-231 cells, shMAFF also resulted in decreased metastatic burden, indicating that MAFF regulates tumor metastasis in a number of tumor types." (PMID 34262028, 2021). "In this study we have shown that MAFF as a HIF-1-dependent transcription factor regulating tumor invasion and metastasis." (PMID 34262028, 2021). "Since IL11 appears to be a direct target of MAFF while other gene regulation seems to be more cell type specific, we decided to focus on the role of MAFF-mediated IL11 expression in tumor cell invasion." (PMID 34262028, 2021). "Taken together, these data demonstrate that MAFF is a positive regulator of tumor cell invasion and metastasis by activating IL11/STAT3 pathways when binding to BACH1, especially under hypoxic conditions." (PMID 34262028, 2021). "Analysis of staining intensity showed that MAFF expression was significantly higher in lymph node metastases when compared with the corresponding primary tumors, suggesting the role of MAFF in tumor progression and metastasis." (PMID 34262028, 2021). "Tumor tissues exhibited significant colocalization of MAFF and HIF-1 (66% colocalization), MAFF and IL11 (94% colocalization), and BACH1 and IL11 (75% colocalization), suggesting their interactive role in cancer." (PMID 34262028, 2021). "When BACH1 or both BACH1 and MAFF were inhibited, tumor cell invasion and tube formation of HUVEC cells were also significantly decreased." (PMID 34262028, 2021). "In contrast to LOX and AKAP12, we found that MAFF transcriptionally regulates a different set of target genes to promote tumor invasion and metastasis." (PMID 34262028, 2021). "In contrast to orthotopic tumor growth, lung colonization after tail vein injection was largely reduced when MAFF was knocked down in MDA-MB-231 cells." (PMID 34262028, 2021). "In glioblastoma, overexpression of RBFOX1 was found to increase the blood-tumor barrier permeability by increasing the stability of MAFF, which promoted doxorubicin delivery across the blood-tumor barrier, resulting in apoptosis of glioma cells." (PMID 33816259, 2021). "As we observed from esiRNA screening, knocking down MAFF significantly reduced tumor cell invasion and migration through type I collagen and Matrigel-coated transwell membranes." (PMID 34262028, 2021).
tumor (continued). "Here, we provide strong evidence that the small MAF protein MAFF is a key regulator of tumor invasion and metastasis, especially under hypoxic conditions." (PMID 34262028, 2021). "Expression of phospho-STAT3 and MECA32 staining was also examined from primary tumor tissues to examine the effect of MAFF and IL11 on STAT3 pathways and microvessel density." (PMID 34262028, 2021). "In our in vivo studies, we also show that MAFF knockdown decreases tumor lung metastasis in both tail vein injection and spontaneous metastasis models." (PMID 34262028, 2021). "Taken together, our findings highlight the importance of MAFF as a transcription factor regulating tumor progression under normoxia and hypoxia." (PMID 34262028, 2021). "Our genome-wide analysis using RNA- and ChIP-sequencing determined IL11 as a direct target of endogenous MAFF, which is responsible for an invasive tumor phenotype." (PMID 34262028, 2021). "CircITCH may facilitate HCC progression by acting as a sponge for miR-224-5p, thereby preventing its inhibitory effect on MafF, a transcription factor involved in oncogene activation and tumor growth." (PMID 41465470, 2025). "In metastatic breast cancer, elevated MAFF expression was associated with activation of the IL-11/signal transducer and activator of transcription 3 (STAT3) pathway, and inhibition of MAFF expression reduced tumor metastasis, suggesting a role in promoting tumor invasion and dissemination." (PMID 41146237, 2025). "Furthermore, the C0 MAFF+ tumor cell subtype displayed elevated levels of nCount RNA, nFeature RNA, and stemness expression, indicating a higher degree of malignancy and differentiation potential for these cells." (PMID 40936936, 2025). "MAFF was found to serve as a hypoxia gene to promote tumor invasion and metastasis." (PMID 39412062, 2024). "MAFF inhibition significantly decreased metastasis from the primary tumor to the lung." (PMID 34262028, 2021). "To determine whether MAFF-induced IL11 affects tumor cell invasion through STAT3 signaling, we first measured phospho-STAT3 protein levels." (PMID 34262028, 2021). "This controversy over whether MAFF has a cancer-promoting or anti-tumor effect makes it necessary to confirm our findings with larger samples and experiments." (PMID 33315534, 2021). "To identify genome-wide downstream targets of MAFF in tumor cells that are involved in tumor invasion and metastasis, we performed high throughput RNA-sequencing of MDA-MB-231 cells exposed to normoxia or hypoxia for 24 hours, with or without genetic inhibition of MAFF by siRNA." (PMID 34262028, 2021). "To determine whether MAFF inhibition altered tumor metabolism, we measured lactate and pyruvate levels from the cell media." (PMID 34262028, 2021). "The metastatic role of MAFF was further investigated using a second metastatic tumor model." (PMID 34262028, 2021). "In addition, exogenously expressed IL11 rescued the decreased invasion in MAFF knockdown cells, suggesting that MAFF regulates tumor cell invasion through the IL11 pathway." (PMID 34262028, 2021). "However, compared to shSCR group, MAFF knockdown MDA-MB-231 tumors with IL11 overexpression displayed similar levels of tumor metastasis as shSCR controls, mirroring the rescue effects from our in vitro studies." (PMID 34262028, 2021). "To investigate the role of MAFF in metastasis in vivo, we used orthotopic mouse tumor models." (PMID 34262028, 2021). "MAFF could promote tumor invasion and metastasis through IL11 and STAT3 signaling." (PMID 36275774, 2022). "Functionally, MAFF-mediated repression of CPT2 diminishes fatty acid oxidation and enhances tumor invasion, underscoring a dual role whereby MAFF drives tumor progression yet primes cells for ferroptotic death." (PMID 42209456, 2026). "To determine if MAFF and its downstream targets, IL11/STAT3, play a significant role in tumor metastasis, we performed in vivo experiments using MDA-MB-231 cells injected into the mammary fat pad of NSG mice." (PMID 34262028, 2021).
tumor (continued). "Knocking down BACH1 or both MAFF and BACH1 decreased tumor cell invasion and tube formation of HUVEC cells." (PMID 34262028, 2021). "Here, we demonstrate that MAFF, which is induced by HIF-1 under hypoxia, binds with BACH1 and promotes tumor invasion and metastasis by transcriptionally activating IL11 and promoting STAT3 pathways." (PMID 34262028, 2021). "Consistent with our previous in vivo studies using athymic nude mice, knocking down MAFF did not change primary tumor growth rates." (PMID 34262028, 2021). "In MDA-MB-231 cells, MAFF knockdown did not alter in vitro cell growth under normoxia or hypoxia, indicating that MAFF does not play a key role in primary tumor growth." (PMID 34262028, 2021). "Our data indicate that while MAFF does not affect primary tumor growth, it promotes disease progression by increasing the invasive and metastatic behavior of tumor cells." (PMID 34262028, 2021). "In addition, MAFF is an indispensable binding partner of CNC and BACH proteins, and impacts multiple pathways that are necessary for tumor progression." (PMID 34262028, 2021). "In this study, we identify v-maf musculoaponeurotic fibrosarcoma oncogene homolog F (MAFF) as a potent regulator of tumor invasion without affecting cell viability." (PMID 34262028, 2021). "Tumor cell proliferation as determined by Ki67 staining was also not affected by MAFF knockdown." (PMID 34262028, 2021). "Our results suggest that high MAFF levels enhance tumor cell invasion regardless of NRF2 status." (PMID 34262028, 2021). "In the orthotopic mouse model, we also confirm that overexpression of IL11 restores the levels of tumor metastasis and expression of phospho-STAT3 expression in the absence of MAFF, supporting a critical role of IL11 in MAFF-mediated tumor metastasis." (PMID 34262028, 2021). "Consistent with MAFF knockdown, we observed that inhibition of BACH1, IL11, or STAT3 did not change primary tumor growth, suggesting that their main role in cancer was not the regulation of cell proliferation in our experimental settings." (PMID 34262028, 2021).
cancer (18 papers, 2018 to 2025). A tumor composed of atypical neoplastic, often pleomorphic cells that invade other tissues. "Another hub gene, MAFF, is also hypoxia related and has been proven to be tightly associated with invasion and metastasis of cancer via HIF/NF-κB pathway." (PMID 34917146, 2021). "MAFF, a transcription factor, correlates with inflammatoryresponses and immune cell infiltration in certain cancers." (PMID 40985687, 2025). "YY1 is an important mediator of enhancer–promoter interactions, and the expression of YY1 and MAFF in the cancer-epithelial cells was confirmed using the matching scRNA-seq dataset." (PMID 37685859, 2023). "Although the function of NFE2L1/2 and its binding partners (MafG, MafF, and MafK) to form heterodimers in cancer has been extensively studied, their distinguishing roles in the regulation of PD-L1 and immune evasion are poorly understood." (PMID 37985752, 2023). "To identify direct NRF3 target genes in cancer cells, we searched ChIP sequence data for MAFF and MAFK in the ChIP-Atlas database because ChIP sequence data for NRF3 were not available and because these sMaf proteins are heterodimerization partners of NRF3." (PMID 31288376, 2019). "Furthermore, targeting regulators of ferroptosis, such as AIFM2, glutathione synthetase (GSS), GPX4, FA complementation group D2 (FANCD2), and MAF BZIP transcription factor F (MAFF) can sensitize specific cancers to radiotherapy-dependent ferroptosis." (PMID 38844964, 2024). "There is also evidence that MAFF regulates cancer pathogenesis." (PMID 34151731, 2021). "Until now, the role of MAFF in cancer has been poorly recognized." (PMID 34262028, 2021). "Another PIRTF of LSCC, MAFF, has also been reported in several cancers other than LSCC." (PMID 33315534, 2021). "Moreover, MAFF is involved in diverse physiological and pathological processes including hematopoiesis, cellular stress response, and cancer development." (PMID 34961819, 2021). "Our studies show that FOS is a main regulator of C0 MAFF+ TCs in LUAD, polarizing macrophages via MIF and rewiring lipid metabolism to support cancer." (PMID 40936936, 2025). "The basal‐cancer‐specific BATF and MAFF activities were monotonically upregulated during transformation." (PMID 38582099, 2024). "The activity of GATA‐family and MEF2C TF was upregulated in luminal cancer cells, while that of the ATF (BATF/MAFK/MAFF/BACH1) TF was upregulated in basal cancer cells." (PMID 38582099, 2024). "To further support these conclusions, we analyzed the cancer cell line database across all members of the NFE2:MAF family including MAFG, MAFF, MAFK, NFE2L1, and NFE2L2." (PMID 37985752, 2023). "Moreover, analysis of the gene expression and survivability data for patients in the cancer genome atlas (TCGA) database revealed that the overall survival time of CAC patients with high MAFF gene expression was substantially longer than that of patients with low MAFF gene expression (p[HR]=0.038)." (PMID 35369066, 2022). "In this case, aging hypomethylated dmCpG sites tended to display a more marked enrichment of most of the cancer hypomethylation factors and, additionally, revealed the presence of other family‐ or function‐related proteins, like FOSL1/2, MAFF, MAFK, and STAT3." (PMID 29504244, 2018).
infection (6 papers, 2008 to 2026). The state of being infected such as from the introduction of a foreign agent such as serum, vaccine, antigenic substance or organism. "The data suggest a role of MAFF in parturition and/or infection‐induced preterm labour through modulation of inflammatory processes in the microenvironment." (PMID 30669188, 2019). "At 3 wpi, Ml MAFF induced fully developed nodules that were largely colonized (nodule colonization = 67.1 ± 13.5%) and contained transcellular infection threads." (PMID 30775775, 2019). "Upon Ml MAFF inoculation, infection threads were visible on top of the growing primordia, and underlying cells were infected." (PMID 30775775, 2019). "Absent from MAFF locus 5 is pthXo6, although previous evidence indicates that OsTFX1, a host gene expressed in a pthXo6-dependent manner, is induced upon infection with MAFF." (PMID 18452608, 2008). "In the context of preterm labour, induction of pro‐inflammatory cytokine levels by infection or stress may thus precede the activation of MAFF." (PMID 30669188, 2019).
neurological disorders (1 paper, 2023). "The small musculoaponeurotic fibrosarcoma oncogene homolog F (MafF), codified by the MAFF gene, belongs to a family of basic leucine zipper transcription factors implicated in different neurological disorders." (PMID 37508918, 2023).
MAFF also shares sentences with these, for which no sentence is quoted: lung adenocarcinoma (3 papers); colorectal cancer (2); neurodegenerative disease (2); nevus (2); Alzheimer disease (1); Barrett esophagus (1); brain tumor (1); cardiovascular disease (1); coronary artery disease (1); diffuse large B-cell lymphoma (1); endometriosis (1); geographic atrophy (1); immune system disorder (1); injury (1); ischemia (1); lung disease (1); measles (1); pancreatic cancer (1); prostate carcinoma (1); renal carcinoma (1); retinal disease (1); toxoplasmosis (1); tuberculosis (1).